CD4 (CD4 molecule)
Diseases named in the same sentence as CD4 in open-access papers (continued):
Sharing a sentence is not in itself a finding about the gene and the disease.
breast cancer (continued). "In breast cancer, ovarian cancer, cervical cancer, colorectal cancer, and prostate cancer, CD4+ T cells lacking CD40L induce B cells to differentiate into granular B-secretory cytotoxic cells by producing IL-21." (PMID 31662750, 2019). "Considering the complex composition of breast cancer immunoinfiltrates (including CD8+ and CD4+ T-lymphocytes, regulatory T-cells or macrophages), future studies will have to show whether the -652 InsDel polymorphism takes an influence on TIL composition." (PMID 31467295, 2019). "We investigated the effect of breast cancer cells on the expression level of ICs on Tregs (defined as CD4+CD25+FoxP3+Helios+), in addition to the effect of anti-PD-1, anti-PD-L1 or both mAbs on the expression of ICs on Tregs in the presence of breast cancer cells." (PMID 31614877, 2019). "Unlike the blockade of PD-L1, anti-PD-1 alone did not further upregulate TIM-3 and LAG-3 co-expression on CD4+CD25+FoxP3+Helios+ Tregs in the presence of breast cancer cells." (PMID 31614877, 2019). "JAK1 expression levels had significant positive correlations with infiltrating levels of CD8+ T cells, CD4+ T cells, macrophages, neutrophils, and dendritic cells in breast cancer and not with other B cells." (PMID 31790361, 2019). "Next, we examined the expression of PD-1, CTLA-4, LAG-3, TIM-3, FoxP3, and Helios in CD4+CD25− T cell subset in the presence or absence of breast cancer cells." (PMID 31614877, 2019). "In this study, anti-CTLA-4 immunotherapy was combined with tremelimumab and exemestane and an elevation in the levels of peripheral CD4+ and CD8+ T cells, which express inducible co-stimulatory molecules (ICOS), was observed, suggesting a role for anti-CTLA-4 inhibitors in breast cancer treatment." (PMID 31366131, 2019). "In this study, we extended our previous findings demonstrating increased CD4+ T cells drained from tumor microenvironment of breast cancer patients by evaluating the different CD4+ T cell subsets isolated from non-IBC and IBC patients." (PMID 31145753, 2019). "In certain tumors such as breast cancer, the presence of memory phenotype T cells are a prognostic indicator for anti-tumor responses, with an increase in TCM-like and decrease in TEM-like CD4+ cells in the lymph nodes of patients progressing from stage I to stage III disease." (PMID 31379821, 2019). "In this study, we aimed to examine the effect of breast cancer cells on the expression level of ICs on CD4+ T cell subsets, including CD4+CD25−, CD4+CD25+, and CD4+CD25+FoxP3+Helios+ Tregs, in the absence and presence of anti-PD-1 mAb, anti-PD-L1 mAb or both mAbs." (PMID 31614877, 2019). "It has been reported that at different time points, both the CD4+ TH cells and CD8+ TC cells could have similar or opposing roles during breast cancer progression." (PMID 30237863, 2018). "However, on the contrary, an observation from a cancer study indicated that sclareol reduced the number of splenic CD4+, CD25+, FoxP3+, and Treg cells in breast cancer mice." (PMID 29751535, 2018). "Only one HIV-positive patient exhibited a CD4 count over 1000 cells/μL, and presented with stage 4 breast cancer, which did not follow the trend demonstrated in other groups." (PMID 31754516, 2018). "The percentage of CD3+CD4+CD127negCD25+FoxP3+ Treg cells were significantly higher in patients with breast cancer than in their no-known disease, age-matched counterparts." (PMID 30254632, 2018). "There is a significant body of evidence documenting the important contribution by circulating and tumour-infiltrating T effector (CD4+ and CD8+) and regulatory (FOXP3+ and CTLA-4+) cells and NK cells in immune-mediated breast cancer cell death in women with LLABCs undergoing NAC." (PMID 28913366, 2017).
breast cancer (continued). "On the contrary, patients with gastric and breast cancer showed up-regulation of CD95 expression in peripheral blood CD8 Т cells, while head and neck cancer patients displayed increased numbers of CD95+ cells in both CD4 T helper and CD8 T killer subsets." (PMID 29075318, 2017). "A fluorescent analysis of CD4+, CD8+ and CD20+ lymphocytes in breast cancer using fluorescently tagged antibodies and the AQUA image analysis system demonstrated an association of AQUA scores and pathologic complete response in a cohort of patients treated with neoadjuvant chemotherapy." (PMID 28923066, 2017). "Therefore, this trial will be the first study to provide valuable clinical data of the impact of everolimus on several important peripheral blood immune cells, including CD4+ T cells, CD8+ T cells, Ths, Tregs, and NK cells in patients with breast cancer." (PMID 29070044, 2017). "In addition, the culture supernatant ofASCs isolated from breast cancer patients withpathological stage III had an ability to inducedifferent cytokines such as IL-4, TGF-β1 andIL-10 in PBLs and to upregulate CD4+CD25highFoxp3+ T regulatory cells." (PMID 28367424, 2017). "The subsets of T cells (CD4+, CD8+, FOXP3+(forkhead box protein 3), and PD-1+(programmed death molecule 1)) infiltrating breast cancer, however, can have different pathobiological significance and prognostic characteristics and are a matter of continuing debate." (PMID 27777963, 2016). "Tumor-infiltrating regulatory T cells have been reported to stimulate mammary cancer metastasis through RANKL-RANK signalling; and RANKL-positive expression colocalized with CD4+ and CD8+ T lymphocytes in acutely rejected kidney tissue in an animal model of kidney transplantation." (PMID 27631617, 2016). "WN-Fc-1 and WN-Fc-2 fusion proteins bound to 4T1 murine mammary carcinoma cell line, while no significant binding was seen with human peripheral blood CD4+ T lymphocytes." (PMID 27713158, 2016). "We also determined whether CD4+ and CD8+ T cells had different roles and prognostic value for clinical outcomes in breast cancer patients with different ER or HER2 expression status." (PMID 25968569, 2015). "However, the overall changes and dynamic distributions of tumor-infiltrating CD4+ and CD8+ T cells had similar trends in both breast cancer models except the earlier peak of Th1 cells in the E0771 model than that in the 4T1 tumor model with tumor progression." (PMID 25968569, 2015). "We showed that both CD4+ and CD8+ T cells involved the immune responses but with distinct dynamic trends in breast cancer development, suggesting their potentially different roles in directing breast cancer progression." (PMID 25968569, 2015). "Based on these results, the major challenge for augmenting the success of anti-tumor immunity and immunotherapy against breast cancer is to develop effective strategies to increase CD8+ T cells and keep the optimal balance of CD4/CD8 in the tumor microenvironment." (PMID 25968569, 2015). "Limiting the analysis to non-metastatic elderly breast cancer patients only, we still observed a similar negative impact on survival for the patients whose CD4+ T-cells produced IL-5 and/or IL-17 (p = 0.02)." (PMID 26500775, 2015). "Moreover, we determined CD4+ T cell subset and CD8+ T cell infiltration in primary breast cancer tissues from cancer patients and retrospectively analyzed their correlations with prognostic factors and clinical outcomes." (PMID 25968569, 2015). "In contrast, intra-tumoral CD4+ T cells have negative prognostic effects on breast cancer patient outcomes." (PMID 25968569, 2015). "Our results further confirmed that CD8+ T cells are the key effector cell population and have positive effects on anti-tumor immunity and patient clinical outcomes, and that CD4+ and CD8+ T cells have opposing prognostic effects for breast cancer patient outcomes." (PMID 25968569, 2015).
breast cancer (continued). "Immunotherapy, but not chemotherapy, enhances CD4+ immunity and affords long-term control of breast cancer growth and resistance to new tumor foci." (PMID 25409195, 2014). "Interestingly, a comprehensive analysis of the immune characteristics of a small group of breast carcinomas also showed an increase of CD8 and a decrease of CD4 and CD20 lymphocytes after chemotherapy." (PMID 25432519, 2014). "In patients with aggressive breast cancers, these pDC exhibit suppressed IFN-α secretion and are able to sustain CD4+ Treg expansion, and the suppression of IFN-α production by pDC has been attributed to tumor-derived TGFβ and TNFα mediated-signaling in these cells." (PMID 23874338, 2013). "Curiel demonstrated in a phase 0/1 trial that Ontak at 9 or 12 μg/kg decreased the number of blood Treg and the suppression mediated by the CD4+CD25+ blood T-cell population in patients with advanced stage epithelial carcinomas, including cases of breast carcinoma." (PMID 23861693, 2013). "We detected an increase in CD4+CD25+CD127- regulatory T cells in the CD3+T cell population from co-cultures of IDO-expressing CHO cells and CD3+T cells isolated from the peripheral blood of patients with breast cancer." (PMID 21917155, 2011). "We previously reported in breast cancer patients that, in addition to conventional CD4+ and CD8+ αβ T cells, individual tumors and most pleural effusions contained significant fractions of unconventional double positive (DP) CD4+CD8+ αβ T cells." (PMID 20052413, 2010). "The intensity of lymphocytic infiltrate and probably the relative abundance of the CD4+ and CD8+ T-lymphocytes may represent important survival prognostic biomarkers for canine mammary carcinomas." (PMID 20525350, 2010). "Our data demonstrated that from the immunophenotypic standing point, the analysis of tumor infiltrating CD4+ and CD8+ T-cells may represent important complementary prognosis biomarkers to be further investigated in canine mammary carcinomas." (PMID 20525350, 2010). "Analysis of CD107a and CD127 in PBMCs from patients with breast cancer showed a trend, but not statistically solid differences, towards lower values of IL-7R expression on CD4+CD107a+ T-cells." (PMID 19657390, 2009). "For example: In ER + breast cancer (BC), Kv11.1 channel-induced senescence triggered SASP-dependent activation of CD4 + Th1 cells and memory T cells, leading to TNF-α-mediated killing of senescent tumor cells." (PMID 40781676, 2025). "Importantly, the CD4+ T/CD8+ T cell ratio was significantly increased in calcipotriol- compared with EtOH-treated tumors, demonstrating that CD4+ T cells constituted the majority of tumor-infiltrating T cells in calcipotriol-treated PyMt mammary tumors." (PMID 39782693, 2025). "Consistent with the dominant role of CD4+ Th2 cells in mediating TSLP’s antitumor effects during early carcinogenesis, topical TSLP induction by calcipotriol treatment results in the induction of CD4+ Th2 cell immunity against late-stage breast cancer progression." (PMID 39782693, 2025). "In basal-like breast cancer, the expression of chemokine CXCL12 and its receptor CXCR4 is increased significantly under hypoxic environment compared to other BC subtypes, which increases the degree of infiltration of CD4+T cell subsets with significant immunosuppressive effect, such as Tregs." (PMID 40438111, 2025). "When mammary tumors were pretreated with image-guided fractionated radiation therapy (IGRT) followed by anti-TAG72-IL-2 therapy, an improved tumor growth inhibition was observed along with an increased tumor infiltration of IFNγ+ CD8+ T cells and a significant reduction in Foxp3+ CD4+ cells." (PMID 40361381, 2025). "Therefore, it is speculated that high levels of CD4+ T cell infiltration and CD8+ T cell infiltration are related to the poor prognosis of breast cancer." (PMID 39669558, 2024).
breast cancer (continued). "During breast cancer progression, DCs engage in phagocytosis of apoptotic tumor cells, process and present tumor antigens on MHC-I and MHC-II molecules, migrate to local lymph nodes, and present antigens to naive CD4+ and CD8+ T cells to elicit an anti-tumor immune response." (PMID 38533507, 2024). "In addition, the CD4+_ISG15, CD4+_MKI67 and IFN-I signatures identified in tumor-infiltrating CD4+ T cells showed enrichment in the same tissue region in a human breast cancer specimen subjected to spatial transcriptomic profiling (10x Visium)." (PMID 38383773, 2024). "Consequently, patients with advanced breast cancer may witness an increase in CD8+T cells and experience a significant decrease or even reversal of the CD4+/CD8+ ratio." (PMID 38263363, 2024). "Additionally, a study on breast cancer, indicated that FAP+PDGFRβ+ CAF in tissues not only released CXCL12 to promote the migration of CD4+CD25+ T cells, but also expressed CD73, dipeptidyl peptidase IV (DPP4) and B7H3 to promote the conversion of CD4+ T cells to FOXP3+ Treg cells." (PMID 36759842, 2023). "For example, early diagnosed older breast cancer patients showed increased frequencies of CD8+ T cells, their cytotoxic sub-types and CD4+ effector memory T cells after 3 months of chemotherapy, although the frequencies of CD8+ central memory T cells and the CD4+/CD8+ ratio decreased." (PMID 37324393, 2023). "The polarization of CD4+ T helper (Th) lymphocytes (mainly Th1 and Th2) may differ in breast cancers with different outcomes, but this has not been fully validated." (PMID 36694223, 2023). "Our study show reverted ratios of CD4+/CD8+ T cells in rectal cancer tissues and progressive disease (R vs. NR: 0.787 vs. 0.556, p < 0.05; progressive vs. stable: 0.83 vs. 1.83, p < 0.05) than normal value of around 2.0, which were also observed in cervical cancer and breast cancer." (PMID 35534879, 2022). "Thus, decreased percentage of CD4+CD25+Foxp3+ in both spleen and breast tumor tissue by naringenin and CPT might be of significant benefit for breast cancer immunotherapy." (PMID 35606804, 2022). "Further studies have shown that the expression of IDO1 was correlated with the expression of CD4, CD3, and CD8 as well as prognosis in colon cancer, but the expression of IDO1 was not related to the expression of CD3 and CD8 in the hormone receptor-positive breast cancer." (PMID 35187162, 2022). "The intrinsic modulatory mechanism of cytokines secreted by CD4+ TH cells influencing ECM remodeling would be our study field in the future, which is a crucial dimension to explain the correlation of the TME with prognosis in breast cancer and find potential combined therapies in the clinic." (PMID 35795662, 2022). "Among the nine immune cell types, the poor survival group (cluster 4) had the lowest scores in memory resting CD4 T cells and resting mast cells, and the highest scores in follicular helper T cells, M0 macrophages, and activated dendritic cells in both METABRIC and TCGA breast cancer studies." (PMID 35286348, 2022). "This study finds that peripheral NK and T cells are activated by MWA of breast cancer partly dependent on B cell and CD4+ T cell collaboration, and MWA combined with immune checkpoint inhibitor may be a promising strategy for the treatment of early‐stage breast cancer." (PMID 35403824, 2022). "In brief, our results showed that the inhibition of S100A7/cPLA2 signaling could increase the infiltration of proliferating and activated CD4+ and CD8+ TILs in breast TME and may mount an enhanced anti-tumor immune response against aggressive metastatic breast cancer cells." (PMID 35135586, 2022). "Although the correlation between CAND1 and the infiltration of immune cells in breast cancer has not been studied before, a published report showed that the infiltration of CD4 memory T cells and neutrophils correlates positively with CAND1 in lung adenocarcinoma." (PMID 36292029, 2022).
breast cancer (continued). "In addition, in multivariable models of CD8, CD4, CD163, and GeparSixto scores, both HER2 and TNBC status significantly contributed to each model reinforcing the importance of investigating TME metrics within specific breast cancer subtypes." (PMID 36376974, 2022). "MSU42011, in both the MMTV-Neu model of HER2-positive breast cancer and the A/J lung cancer model, increased anti-tumor CD8 T cells, as seen by increased INFγ levels (MMTV-Neu, p = 0.0026), increased ratios of CD8:CD4, CD25 T cells, and decreased immunosuppressive FOXP3+ T cells." (PMID 34638488, 2021). "Notably, anakinra treatment prevented breast cancer progression with a substantial decrease in the proportion of IL-13 producing tumor-infiltrating CD4+ T cells and a concomitant increase of IFN-γ producing CD4+ T cells in a humanized mouse model." (PMID 33686176, 2021). "In previous studies, CD8+ T cells were considered to be the crucial effector cells mediating effective antitumor immunity, resulting in better clinical outcomes, whereas intra-tumoral CD4+ T cells have negative prognostic effects on breast cancer patient outcomes." (PMID 34298668, 2021). "Our previous study first revealed that tumor-infiltrating CD4+ T cell, CD8+ T cell, macrophage, and neutrophil showed a positive correlation with MARCH5 expression, whereas macrophage M2 is the main cluster of cells involved in MARCH5 regulation of breast cancer." (PMID 34680446, 2021). "Notably, we observed that, different to exhausted T cells which are absent in peripheral blood from patients with breast cancer, senescent CD4+ and CD8+ T cells are expanded in circulation." (PMID 34386013, 2021). "However, the relationship between immune cell subpopulations, such as CD4+, CD8+, and FOXP3+, in breast cancer, especially in triple negative carcinoma (TNC), remains unclear." (PMID 32222891, 2020). "However, the origin, differentiation, and mechanism of activation of CD4+CD25+ T cells in breast cancer patients and the homogeneity and heterogeneity of negative regulation of CD4+ CD25+ T cells remain to be elucidated for breast cancer." (PMID 33029539, 2020). "Our analysis demonstrated that the percentages of CD3+, CD4+ and NK cells, and CD4+/CD8+ ratio were all significantly increased in breast cancer patients treated with Huaier Granule, indicating that immune function of breast cancer patients was improved after Huaier Granule adjuvant therapy." (PMID 32789470, 2020). "However, the relationship between immune cells subpopulations, such as CD4+, CD8+ and FOXP3+, in breast cancer, especially in TNC, remains unclear." (PMID 32222891, 2020). "Therefore, to determine whether immune cell accumulation might be affected by F. nucleatum, we used flow cytometry to compare levels of NK cells, CD4+ T cells and CD8+ T cells between AT3 mammary tumors from F. nucleatum-infected and uninfected mice." (PMID 32591509, 2020). "Moreover, CTLA-4 expressed by breast cancer cells may attenuate CD80/86 DC expression and subsequent restricted maturity can hinder proper CD8+ and Th1 CD4+ effector cells." (PMID 32937885, 2020). "To further reinforce these findings, we demonstrated that in a murine breast carcinoma model, IL-31-expressing tumors contained significantly lower numbers of immunosuppressive cell populations such as CD4+CD25+ T cells, MDSCs and M2 macrophages, but not Tregs." (PMID 32843492, 2020). "However, CD4 expression did not significantly correlate with survival of breast cancer patients overall." (PMID 31852159, 2019). "However, the role and prognostic value of CD4+ T cells has not been extensively studied in breast cancer." (PMID 31475002, 2019). "Moreover, the combination of VEGFR-2 and PD-L1 antibodies induces high endothelial venules (HEVs) to facilitate IFNγ+ CD4+ and IFNγ+ CD8+ lymphocyte infiltration in breast cancer and pancreatic neuroendocrine tumors, finally leading to tumor cell apoptosis and necrosis." (PMID 31835465, 2019).